NEAT1 (nuclear paraspeckle assembly transcript 1)
Diseases named in the same sentence as NEAT1 in open-access papers (continued):
Sharing a sentence is not in itself a finding about the gene and the disease.
colorectal cancer (continued). "The present results elucidate a potential mechanism underlying the tumor-oncogenic role of NEAT1 in colorectal cancer and indicate that NEAT1 could serve as a useful marker and potential therapeutic target in CRC." (PMID 36262350, 2022). "In this sense, whole blood NEAT1 expression may be a novel diagnostic, prognostic, and survival biomarker in colorectal cancer." (PMID 27888635, 2017). "As NEAT1 was proved to be associated with colorectal cancer invasion and metastasis, which may determine tumor recurrence, we further analyzed its association with disease-free survival and overall survival of patients." (PMID 26314847, 2015). "Using independent patient cohorts, we demonstrated for the first time that whole blood NEAT1_v1 and NEAT1_v2 may be valuable diagnostic biomarkers in colorectal cancer." (PMID 26552600, 2015). "In addition, we also investigated critical molecular events such as APC, KRAS, BRAF and PIK3CA mutations and MSI, all of which have been associated with colorectal cancer prognosis to justify the prognostic role of NEAT1." (PMID 26314847, 2015). "Therefore, we conducted the present study to determine NEAT1 expression pattern and its association with clinical features, relapse and prognosis of patients with colorectal cancer." (PMID 26314847, 2015). "Although mechanisms underlying this dynamic equilibrium may be difficult to investigate, it is clear that the differential expression of NEAT1 variants in whole blood has prognostic value in colorectal cancer." (PMID 26552600, 2015). "For example, we previously reported that nuclear-enriched abundant transcript 1 (NEAT1) facilitates colorectal cancer progression by stabilizing the DEAD-box helicase 5 (DDX5) and activating Wnt/β-catenin signaling pathway." (PMID 41484982, 2026). "The continuous research on NEAT1 is of paramount importance in enhancing our understanding of its role in colorectal cancer development." (PMID 39139172, 2024). "Our study aims to resolve these discrepancies by conducting a comprehensive meta-analysis of existing research on NEAT1 in colorectal cancer." (PMID 39139172, 2024). "There is accumulating evidence that NEAT1 facilitates tumor cell growth, migration, and invasion in colorectal cancer via targeting miR‐196a‐5p or miR‐216b or in thyroid carcinoma by regulating miRNA‐214 expression." (PMID 38577722, 2024). "This approach is novel in its application and significant in its potential to clarify the prognostic value of NEAT1 expression in colorectal cancer." (PMID 39139172, 2024). "By systematically analyzing previous studies, we seek to establish a more definitive correlation between NEAT1 expression levels and the progression of colorectal cancer." (PMID 39139172, 2024). "By focusing on NEAT1, researchers can potentially identify novel biomarkers for colorectal cancer, aiding in the early detection and patient stratification." (PMID 39139172, 2024). "High NEAT1 expression is an independent prognostic marker of poor outcome and an important indicator of tumor recurrence in colorectal cancer." (PMID 39830506, 2024). "As such, NEAT1 research holds the promise of significantly improving the diagnosis, prognosis, and treatment of colorectal cancer, ultimately contributing to better patient outcomes and advancements in cancer therapy." (PMID 39139172, 2024). "As a long noncoding RNA, NEAT1’s involvement in the molecular mechanisms of colorectal cancer remains a critical area of investigation." (PMID 39139172, 2024). "Further supporting its multifaceted role, recent evidence also points toward an intriguing interaction between ALKBH5 and NEAT1 in colorectal carcinoma, proposing the ALKBH5-NEAT1 axis as a potential therapeutic target." (PMID 38501918, 2024). "For instance, DDX5 can promote colorectal cancer metastasis by interacting with NEAT1 and β-catenin." (PMID 36011001, 2022).
colorectal cancer (continued). "Subsequently, we extracted RNA from peripheral blood and found that the expression of NEAT1 in peripheral blood of colorectal cancer patients was significantly higher than that of normal people." (PMID 36213831, 2022). "To further verify the expression of NEAT1 in colorectal cancer, we collected clinical samples of colorectal cancer patients including peripheral blood and tissue samples as well as peripheral blood of normal people." (PMID 36213831, 2022). "It is showed that NEAT1 activates Wnt/β-catenin signaling and promotes colorectal cancer progression via interacting with DDX5." (PMID 36213831, 2022). "LncRNA NEAT1 activates Wnt/β-catenin signaling and promotes colorectal cancer progression via interacting with DDX5." (PMID 35477447, 2022). "Consistently, NEAT1 also induces autophagy by targeting miR-34a and miR-204 as a competing endogenous RNA (ceRNA) in colorectal cancer and HCC, respectively, resulting in the upregulation of autophagy-related proteins ATG9A, ATG4A, and ATG3." (PMID 36430876, 2022). "In-vitro functional studies indicated that NEAT1 knockdown suppressed the proliferation and migration of colorectal cancer cells by mediating inflammatory response." (PMID 36213831, 2022). "CCK-8 assay showed that the proliferation ability decreased significantly in NEAT1 knockdown colorectal cancer cells." (PMID 36213831, 2022). "NEAT1 indirectly activates the Wnt/β-catenin signaling pathway through DDX5 to promotes colorectal cancer progression." (PMID 35992805, 2022). "In this study, we first found a significant increase of NEAT1 expression in serum from patients with colorectal cancer." (PMID 36213831, 2022). "In conclusion, knockdown NEAT1 decreases the proliferation and migration of colorectal cancer cells and increases the apoptosis of colorectal cancer cells." (PMID 36213831, 2022). "The expression of NEAT1 in colorectal cancer cells HT29, RKO, and SW480 was significantly higher than that in normal cells NCM460 and so does the supernatant medium." (PMID 36213831, 2022). "Functional studies in vitro showed that NEAT1 increased the proliferation and migration of colorectal cancer cells and decreased the apoptosis of colorectal cancer cells." (PMID 36213831, 2022). "The Wnt/β-catenin signaling pathways is also activated in colorectal cancer by the lncRNA NEAT1 (nuclear-enriched abundant transcript 1), which modulates the miR-34a/SIRT1 axis." (PMID 36012617, 2022). "In accordance with our study, Lnc NEAT1 activates Wnt/β-catenin signaling and contributes to colorectal cancer progression via DDX5." (PMID 35850692, 2022). "lnc‐NEAT1 acts as an oncogene to sponge miR‐486‐5p, and its suppression downregulates the malignant progression of colorectal cancer." (PMID 34890108, 2022). "Studies have shown that NEAT1 expression is upregulated in colorectal cancer tissues, and a higher level of NEAT1 contributes to the poor overall survival and disease-free survival." (PMID 36011001, 2022). "Mechanistically, NEAT1 triggers off the proliferation and migration of colorectal cancer cells through promoting the inflammatory reaction." (PMID 36213831, 2022). "In the present study, we also observed that NEAT1 knockdown or miR-216b overexpression remarkably attenuated the ability of cell viability, apoptosis, and invasion on colorectal cancer cells." (PMID 36262350, 2022). "In-vivo, knockdown of NEAT1 inhibits tumor growth and inflammation-related gene expression which further confirm our proposal that NEAT1 regulated colorectal cancer progression through inflammatory response." (PMID 36213831, 2022). "These three studies all found that NEAT1 promoted the proliferation of colorectal cancer cells through different ceRNA signal axis." (PMID 36213831, 2022). "Abnormal high expression level of NEAT1 in colorectal cancer tissues and cells leads to poor prognosis." (PMID 36213831, 2022).
colorectal cancer (continued). "The role of NEAT1 in the colorectal cancer progression was further confirmed by both in-vivo and in-vitro functional experiments." (PMID 36213831, 2022). "For example, lncRNA nuclear paraspeckle assembly transcript 1 (NEAT1) modulated the radiosensitivity of colorectal cancer (CRC) cells by regulating the pyroptosis induced by ionizing radiation through miR-448/GSDME axis." (PMID 35873495, 2022). "To further explore the role of NEAT1 in colorectal cancer progression, we selected 5-week-old male nude mice and injected cancer cells to observe their tumorigenesis." (PMID 36213831, 2022). "Wound healing assay showed that the migration ability of colorectal cancer cells decreased significantly after NEAT1 knockdown." (PMID 36213831, 2022). "Then, we further performed a literature search and selected 2 miRNAs (miR-342-3p/miR-650) and 2 lncRNAs (NEAT1/XIST) that with related reports in UC or UC-related colorectal cancer." (PMID 36419192, 2022). "Another study showed that the long non-coding RNA (lncRNA) NEAT1, which competes with miR-193a-3p, is up-regulated in colorectal cancer samples and correlates with poor outcome." (PMID 33833999, 2021). "In colorectal cancer cells, NEAT1 directly binds to the DDX5 protein, maintains its stability, and activates the Wnt signaling pathway." (PMID 32922184, 2020). "Colorectal cancer progression is promoted by nuclear paraspeckle assembly transcript 1 (lncRNA NEAT1), which competitively binds miR-34a with histone deacetylase sirtuin 1 (SIRT1)." (PMID 32429086, 2020). "Further research showed that the activity of ALDH1 and CD133 was decreased by downregulating the expression of NEAT1 in colorectal cancer cell lines." (PMID 33168814, 2020). "In this study, we observed that NEAT1 was highly expressed in colorectal cancer tissues from patients with recurrence and was also associated with poor recurrence-free survival." (PMID 33168814, 2020). "NEAT1 impacted cell proliferation and apoptosis of colorectal cancer via regulation of Akt signaling." (PMID 32268876, 2020). "Taken together, this study uncovered an essential NEAT1/miR‐193a‐3p/KRAS regulatory axis in colorectal cancer." (PMID 30575330, 2019). "Our findings indicated that NEAT1 activated Wnt signaling to promote colorectal cancer progression and metastasis." (PMID 30185232, 2018). "The long noncoding RNA nuclear-enriched abundant transcript 1 (NEAT1) has been reported to be overexpressed in colorectal cancer (CRC)." (PMID 30185232, 2018). "To assess the functional role of NEAT1 in colorectal cancer cells, first we examined the baseline NEAT1 RNA levels in eight CRC cell lines (RKO, CACO2, SW1116, LOVO, SW480, SW620, HT29, and HCT116) by RT-qPCR." (PMID 30185232, 2018). "Specially, we discovered some meaningful drug-lncRNA-disease correlations (e.g., puromycin-NEAT1-colorectal cancer)." (PMID 28751672, 2017). "NEAT1 expression in colorectal cancer was up‐regulated and related to tumor differentiation, invasion, metastasis, and TNM stage 22." (PMID 27075229, 2016). "Kaplan-Meier analysis showed that patients with colorectal cancer of high NEAT1 expression had worse overall survival compared with patients with tumor of low NEAT1 expression (log-rank test: P < 0.001)." (PMID 26314847, 2015). "High expression of the long non-coding RNA nuclear-enriched abundant transcript 1 (NEAT1) in whole blood has been reported in colorectal cancer patients; however, its’ clinical significance and origin are unclear." (PMID 26552600, 2015). "And little is known about the expression pattern and clinical significance of NEAT1 in colorectal cancer." (PMID 26314847, 2015). "Further research is needed to fully clarify the clinical significance of high neutrophil NEAT1 expression in colorectal cancer patients." (PMID 26552600, 2015). "The expression level of NEAT1 was detected in 239 matched colorectal cancer samples and adjacent, histological normal specimens by real-time PCR, and normalized to ACTIN." (PMID 26314847, 2015).
colorectal cancer (continued). "In the present study, we investigated NEAT1 expression in 239 cases of clinical colorectal cancer specimens and matched normal tissues." (PMID 26314847, 2015). "Kaplan-Meier analysis was used to evaluate the disease-free survival of patients with colorectal cancer and NEAT1 expression." (PMID 26314847, 2015). "Real time PCR results revealed that both total NEAT1 and NEAT1_2 expression was increased in colorectal cancer compared with that in normal specimens (P < 0.001)." (PMID 26314847, 2015). "In the present study, we also investigated the possible sources contributing to the differential whole blood expression of NEAT1 between colorectal cancer patients and NCs." (PMID 26552600, 2015). "So further research on the polyadenylation signals in NEAT1 edition and its function in colorectal cancer is required." (PMID 26552600, 2015). "Considering that immune cells comprise the majority of peripheral blood cells, we also determined NEAT1 expression from different subgroups of immune cells between colorectal cancer patients and NCs." (PMID 26552600, 2015). "Results showed that NEAT1 expression in colorectal cancer was up-regulated in 72.0% (172/239) cases compared with corresponding normal counterparts, and related to tumor differentiation, invasion, metastasis and TNM stage." (PMID 26314847, 2015). "Results showed that patients with high NEAT1 expression in colorectal cancer tissues had unfavorable disease-free survival in comparison to those with low NEAT1expression (log-rank test: P < 0.001)." (PMID 26314847, 2015). "In conclusion, we proved that NEAT1 expression in clinical colorectal cancer was associated with tumor differentiation, invasion and metastasis, indicating that NEAT1 may be a mediator for the functions of oncogene in the differentiation and progression of colorectal cancer." (PMID 26314847, 2015). "This limitation may impact the study’s findings, potentially omitting recent advancements and insights into NEAT1’s role in colorectal cancer, which could affect the overall conclusions and recommendations." (PMID 39139172, 2024). "In the case study, NAGTLDA successfully predicted associations, such as NEAT1-colon cancer, SOX2-OT-prostate cancer, and WT1-AS-colorectal cancer, which were previously unknown in the dataset." (PMID 38233788, 2024). "Also, NEAT1 activates Wnt signaling by interacting with DDX5 to promote colorectal cancer progression." (PMID 36787190, 2023). "NEAT1 knockdown blocked Wnt signaling via miR-34a in colorectal cancer progression." (PMID 36787190, 2023). "In colorectal cancer, however, miR-34a was a target of lncRNA NEAT1." (PMID 36983973, 2023). "The long noncoding RNA NEAT1 has been reported to be overexpressed in colorectal cancer (CRC)." (PMID 36262350, 2022). "Clinically, the expression level of NEAT1 in serum may be a marker for diagnosis and prognosis of colorectal cancer." (PMID 36213831, 2022). "What is more, the results imply that targeting NEAT1-mediated inflammatory response may be a new therapeutic target for colorectal cancer treatment." (PMID 36213831, 2022). "In summary, these results further suggest that NEAT1 may promote colorectal cancer proliferation, invasion, and migration through inflammatory pathway." (PMID 36213831, 2022). "We hypothesize that NEAT1 may promote inflammasome in colorectal cancer to promote tumor cell growth." (PMID 36213831, 2022). "As colorectal cancer development and metastasis are facilitated by the stimulation of the Wnt signaling pathway activated through lncRNA NEAT1, the lncRNA NEAT1/DDX5/Wnt/-catenin axis might be an effective therapeutic target." (PMID 35909905, 2022). "In colorectal cancer, a study showed that NEAT1-2 can inhibit caner proliferation." (PMID 36011001, 2022). "Moreover, NEAT1 can also promote the proliferation and metastasis of colorectal cancer in vivo and in vitro." (PMID 36011001, 2022).
colorectal cancer (continued). "The abnormal expression of NEAT1 is related to the occurrence and development of colorectal cancer." (PMID 36213831, 2022). "As a result, NEAT1 regulate inflammatory response in colorectal cancer." (PMID 36213831, 2022). "LncRNA NEAT1 also could promote the progression of colorectal cancer by activating Wnt/β-catenin signaling through interaction with DDX5." (PMID 35300348, 2022). "To explore the relationship between NEAT1 and the biological process and metabolism and signal pathway of colorectal cancer cells, we used the R package to merge the differential genes of all comparison groups and conduct two-way cluster analysis of the sample group." (PMID 36213831, 2022). "In this study, expression of NEAT1 in colorectal cancer patients was analyzed by bioinformatics." (PMID 36213831, 2022). "Furthermore, NEAT1 increases the proliferation and migration of colorectal cancer cells through inflammatory reaction." (PMID 36213831, 2022). "Additionally, LINC00173.v1 in NSCLC, by downregulating miR-511-5p, and NEAT1 in colorectal cancer, by downregulating miR-205-5p, increased VEGFA expression." (PMID 36012617, 2022). "In CRC, it was illustrated that the NEAT1 expression level was an independent prognostic factor for disease-free survival and overall survival which mechanismly promoted colorectal cancer progression by competitively binding miR-34a resulting in activation of Wnt/beta-catenin signaling pathway." (PMID 36262350, 2022). "However, the specific mechanism of NEAT1 mediated-inflammatory pathway in the progression of colorectal cancer is still unclear." (PMID 36213831, 2022). "As we mentioned, NEAT1 is upregulated in colorectal cancer; thus, the relationship between NEAT1 and CDON in EMPD may be completely different from that in other cancers." (PMID 34895219, 2021). "The nuclear paraspeckle assembly transcript 1 (NEAT1), a newly discovered nuclear-restricted and cancer-associated lncRNA, has key functions in the development of several cancers, showing high expression in colorectal cancer, nasopharyngeal carcinoma and BC." (PMID 33820555, 2021). "LncRNA NEAT1 is a component of nuclear paraspeckle, so we therefore speculated whether NEAT1 could also affect chromatin remodeling and histone modification levels of colorectal cancer cells." (PMID 33168814, 2020). "In summary, these data indicated that knockdown of NEAT1 may decrease the expression of stemness factors to suppress CSC properties of colorectal cancer cells." (PMID 33168814, 2020). "In summary, knockdown of NEAT1 could reduce the expression of stemness factors to inhibit CSC properties of colorectal cancer cells." (PMID 33168814, 2020). "With 10 μg/ml of 5-Fu treatment, CCK-8 assays showed that knockdown of NEAT1 could decrease the resistance of colorectal cancer cell lines to 5-Fu." (PMID 33168814, 2020). "Moreover, NEAT1 expression is downregulated in several cancers, while increased NEAT1 levels are correlated with better overall survival in colorectal cancer patients." (PMID 32194993, 2020). "These include but are not restricted to lncRNAs like HOTAIR, Pvt1, RoR, prostate cancer–associated transcript 1 (PCAT1), ANRIL, H19, nuclear enriched abundant transcript 1 (NEAT1), UCA1, lung adenocarcinoma transcript 1 (LUADT1), colorectal cancer–associated lncRNA (CCAL), and many more." (PMID 30296263, 2018). "For example, in colorectal cancer cell lines, knockdown of NEAT1-1 could inhibit cell invasion and proliferation, whereas knockdown of NEAT1-2 promoted cell growth." (PMID 30374364, 2018). "Furthermore, this puromycin-NEAT1-colorectal cancer correlation was verified by real-time PCR experiment." (PMID 28751672, 2017). "Whole blood NEAT1 expression was significantly increased in colorectal cancer patients." (PMID 27888635, 2017). "Moreover, the high NEAT1 expression was shown to be an independent prognostic marker of poor outcome in colorectal cancer." (PMID 27075229, 2016).